IL9 (interleukin 9)
Diseases named in the same sentence as IL9 in open-access papers (continued):
Sharing a sentence is not in itself a finding about the gene and the disease.
rheumatoid arthritis (continued). "Relative mRNA expression of PU.1, IL-9, IL-17 and IL-9R in control conditions (Th0), Th9- and Th17-inducing conditions in naive and non-naive T cells of healthy donors (HD) and rheumatoid arthritis (RA) patients." (PMID 33995403, 2021). "Although not directly addressed in viral infection models, recent studies have shown that IL-9 produced by ILC2 can prevent sepsis-induced pyroptosis in lung endothelial cells and contributes to the resolution of inflammation during rheumatoid arthritis." (PMID 30893756, 2019).
pulmonary fibrosis (24 papers, 2005 to 2025). Chronic progressive interstitial lung disorder characterized by the replacement of the lung tissue by connective tissue, leading to progressive dyspnea, respiratory failure, or right heart failure. "One, it was possible that in ST2-deficient mice, one or more profibrotic factors other than IL-9 drive pulmonary fibrosis." (PMID 41465219, 2025). "In this report, we describe and reflect on a newly discovered link between ST2 deficiency and TSLP-driven IL-9 elevation in the regulation of pulmonary fibrosis." (PMID 41465219, 2025). "Interleukin-9, the signature cytokine of the Th9 immune response which plays important roles in allergic, autoimmune, and oncological pathologies, has also been implicated as a regulator of lung fibrosis." (PMID 41465219, 2025). "The Th2 cytokine IL-13 may be involved in inflammation and remodeling, which accompanies lung fibrosis, while the antifibrotic effects of IL-9 may be associated with a limitation of the type 2 polarization observed in pulmonary fibrosis." (PMID 21943057, 2011). "In a recent study conducted by Deng, K.M., the role of IL9 was deeply investigated in idiopathic pulmonary fibrosis (IPF)." (PMID 40612945, 2025). "Although, as the Introduction section above reflects, the role that IL-9 plays in pulmonary fibrosis appears to be controversial, its profibrotic role comes to the forefront based on relevant specifics of previous studies combined with our current findings." (PMID 41465219, 2025). "Such blockade of TSLP strongly downregulated pulmonary levels of IL-9 and collagen indicative of attenuation of pulmonary fibrosis as well as upregulated terminal body weight indicative of alleviation of the overall disease severity." (PMID 41465219, 2025). "In fibrotic diseases, Th9 cells and IL-9 play a role, with elevated IL-9 levels observed in mouse models of silicosis fibrosis as well as in patients with idiopathic pulmonary fibrosis (IPF) and cystic fibrosis." (PMID 38879568, 2024). "The study also showed that IL-9 induces pro-fibrotic TGF-β production by AMs, which has been known to be implicated in pulmonary fibrosis exacerbation." (PMID 37681924, 2023). "The degree of pulmonary fibrosis was evaluated with Ashcroft score (the more severe the degree of fibrosis, the higher the Ashcroft score) and we found that neutralizing IL-9 had remarkable lower Ashcroft scores than control group (p = 0.0024)." (PMID 34831433, 2021). "Similar as what we observed in the preventive study therapeutic treatment of neutralizing IL-9 reduces pulmonary fibrosis and collagen secretion of BLM mice." (PMID 34831433, 2021). "In order to clarify the role of IL-9 in pulmonary fibrosis, we administered IL-9 neutralizing antibody to intervene BLM-induced pulmonary fibrosis in mice." (PMID 34831433, 2021). "We used TGF-β (the main fibrogenic growth factor) to simulate the pulmonary fibrosis microenvironment and found that IL-9 promoted the proliferation and activation of mouse primary lung fibroblasts, either alone or in the presence of TGF-β." (PMID 34831433, 2021). "IL-9 neutralizing antibody restores Th1/Th2 balance and reduces pulmonary fibrosis by inhibiting Th2 cell differentiation." (PMID 34831433, 2021). "Previous studies have shown that IL-9 affects a variety of cells, and its role in promoting or inhibiting pulmonary fibrosis varies from cell to cell." (PMID 34831433, 2021). "On the other hand, Th9 cells secrete IL-9, which promotes the proliferation and activation of fibroblasts as well as collagen secretion, eventually leading to pulmonary fibrosis." (PMID 34831433, 2021). "In summary, we first elucidated the role of Th9 cells in promoting pulmonary fibrosis through the secretion of IL-9 and IL-4." (PMID 34831433, 2021). "GM-CSF and IL-9 play a protective role against BLM-induced lung fibrosis through a prostaglandin-dependent mechanism." (PMID 26289430, 2015).
pulmonary fibrosis (continued). "Furthermore, administration of an anti-IL-9 neutralizing antibody attenuated the number of pulmonary Th9 cells as well as severity of pulmonary fibrosis." (PMID 41465219, 2025). "Moreover, the authors also reported that neutralizing IL9 in both preventive and therapeutic settings ameliorates bleomycin-induced pulmonary fibrosis in their mice model." (PMID 40612945, 2025). "Furthermore, in the silica model of lung fibrosis in wild-type (in contrast to the IL-9-overexpressing transgenic) mice, neutralization of IL-9 by a blocking antibody suppressed both pulmonary inflammation and fibrosis." (PMID 41465219, 2025). "IL-9 was highly expressed in the serum in both dcSSc and lcSSc and led to a lower degree of fibrosis and a slower decline in vital capacity at the earliest stage, which suggests IL-9 may be a protective molecule in pulmonary fibrosis." (PMID 35185577, 2022). "However, recent studies have shown that Th9 cells do contribute to pulmonary fibrosis by increasing IL-4-mediated Th2 cell differentiation, and IL-9 neutralisation effectively reduces the degree of pulmonary fibrosis." (PMID 36232511, 2022). "Furthermore, we identified several critical signaling pathways involved in the effect of neutralizing IL-9 on pulmonary fibrosis by proteomics study." (PMID 34831433, 2021). "In addition, we found that neutralizing IL-9 in both preventive and therapeutic settings ameliorates bleomycin-induced pulmonary fibrosis." (PMID 34831433, 2021). "Previous studies have reported that IL-9 affects the progress of pulmonary fibrosis." (PMID 34831433, 2021). "Both our and Sugimoto’s studies suggested that IL-9 promotes pulmonary fibrosis." (PMID 34831433, 2021). "Our hypothesis is different from regarding Th9/IL-9 as a whole in previous studies, and this study is the first to explore the role of Th9 cells in promoting pulmonary fibrosis via IL-9 and IL-4." (PMID 34831433, 2021). "Our results suggest that neutralizing IL-9 may alleviate pulmonary fibrosis by regulating the STAT3 and SMAD2/3 pathways." (PMID 34831433, 2021). "We also found that Th9 cells promote pulmonary fibrosis via IL-9 and IL-4 mediated pathways." (PMID 34831433, 2021). "Th9 cells, which produce IL-9, also play dual roles in pulmonary fibrosis." (PMID 33647885, 2021). "The main cytokine secreted by Th9 cells is IL-9, which exerts its effects on a variety of cells, and whether it promotes pulmonary fibrosis is also controversial." (PMID 34831433, 2021). "In contrast, B cells under the influence of IL-9 participated in the protection against lung fibrosis in a murine model of silica particle-induced lung fibrosis, and their protective effect was associated with the overexpression of prostaglandin-E2 (PGE2) in macrophages." (PMID 28018357, 2016). "Furthermore, CAV1 and several other fibrosis associated cytokines and proteins, including IL-33, IL-9 and MMP28 regulate macrophage differentiation in pulmonary fibrosis in mice." (PMID 25852818, 2015). "Next, we verified whether neutralizing IL-9 could reduce pulmonary fibrosis of BLM mice." (PMID 34831433, 2021). "Moreover, we showed that IL-9 neutralizing antibody ameliorated the degree of pulmonary fibrosis." (PMID 34831433, 2021). "For example, antibody-mediated neutralization of IL9 has been described to decrease lung inflammation and tissue damages caused by oxidative stress in a murine model of COPD and to suppress lung injury and pulmonary fibrosis in mice that were intranasally exposed to silica." (PMID 33801620, 2021). "Furthermore, IL-9 neutralizing antibody alleviates pulmonary fibrosis." (PMID 34831433, 2021). "Moreover, neutralizing IL-9 effectively reduced the degree of pulmonary fibrosis." (PMID 34831433, 2021). "Interestingly, first data about the role of the subset of TH9 cells have been obtained in a model of pneumonitis and fibrosis induced by silica particles; these suggest that IL-9 expression may reduce lung fibrosis and type 2 immune polarization." (PMID 28018357, 2016).
pulmonary fibrosis (continued). "Finally, a practical implication of the second observation is that therapeutic targeting of either ST2 alone or IL-9 alone in human patients with pulmonary fibrosis may be less efficient than simultaneous targeting of these two factors, e.g., with a bispecific neutralizing antibody." (PMID 41465219, 2025). "Additionally, other types of T cells, such as Th2 and Th9 cells, may play a role in some conditions, such as allergic responses and stimulating the proliferation of fibroblasts through the production of cytokines, including interleukin 9 (IL-9), in pulmonary fibrosis." (PMID 39582867, 2024). "It has been reported that IL-9 expressing Th9 cells and IL-9 promotes pulmonary fibrosis in mice, coinciding with monocyte-derived alveolar macrophages (Mo-AMs) expressing Arg1 in the BLM-induced lung fibrosis model." (PMID 38162655, 2023). "In both the silica-induced lung fibrosis mouse model and human patients with idiopathic pulmonary fibrosis (IPF) and cystic fibrosis, IL-9 levels were found to be correspondingly elevated." (PMID 32676074, 2020). "We chose to test cytokines and factors known for their different activities on the development of lung fibrosis: proinflammatory (IL-1β and TNF-α), profibrotic (IL-4 and TGF-β) and antifibrotic mediators (IL-9 and PGE-2)." (PMID 16045809, 2005). "Whereas several biological functions have been attributed to IL-9, its involvement in PH has not been investigated so far, and results from preclinical models of lung fibrosis are controversial." (PMID 33801620, 2021). "As we found an elevated level of IL-9 (the main cytokine secreted by Th9 cells) in BALF from BLM mice, we therefore first investigated the in vitro effect of IL-9 on fibroblasts, the major effector cells of pulmonary fibrosis." (PMID 34831433, 2021).
food allergy (23 papers, 2012 to 2025). Gastrointestinal disturbances, skin eruptions, or shock due to allergic reactions to allergens in food. "IL-9 is a pleiotropic cytokine that has been often associated with intestinal diseases, from food allergy to inflammation." (PMID 38719750, 2024). "Previous studies have revealed that IL-9+ MMC9s (IL-9-producing mucosal mast cells) were a key step in IgE-mediated food allergy susceptibility." (PMID 36364962, 2022). "Previous studies have shown that mast cell-derived IL-9 can promote susceptibility to IgE-mediated experimental food allergy." (PMID 32228589, 2020). "The ability to impair barrier function and predispose to food allergy points to IL-9 as a critical determinant in the predisposition to several gastrointestinal diseases such as CD." (PMID 31867008, 2019). "Importantly, mTOR-driven IL-9 production has been associated with pathology and mast cell hyperplasia in experimental food allergy." (PMID 41030439, 2025). "Moreover, mast cell-derived IL-9 enhances the susceptibility to IgE-mediated experimental food allergy." (PMID 34944921, 2021). "IL-9 gene expression is also elevated in the gut of individuals with food allergies; it is a cytokine that promotes mast cell expansion and has been shown to be derived from Th2 cells in food allergies." (PMID 39594870, 2024). "IL-9 is a key cytokine promoting mast cell expansion, and has been shown to be derived from peTh2 cells in food allergy." (PMID 36880703, 2023). "The carotene lycopene reduced the cytokine expression of IL-4, IL-13, and IL-9 by about 60% in an ovalbumin (OVA)-induced food allergy model." (PMID 37998337, 2023). "IL-9-producing mucosal mast cell precursors have been identified, and increased numbers of these cells are drivers of IgE-mediated experimental food allergy." (PMID 35769569, 2022). "Resident mucosal mast cells (MMCs) are also activated by IL-9 which can promote intestinal mastocytosis and food allergy through immunoglobulin ε receptor (FcεR1)-bound IgE in a mouse model." (PMID 35769569, 2022). "Inflammatory MMCs actively produce IL-9 to induce MMC expansion, resulting in increased susceptibility to IgE-mediated food allergy." (PMID 35159139, 2022). "At present, the development of food allergy sensitivity remains poorly understood, but IL-9 is known to induce the release of mucosal tissue mast cells (MMC9), basophils and Th2 cells, and Treg cells play a significant role in this process." (PMID 34177881, 2021). "In the intestinal mucosa, IL-9-producing mucosal mast cells (MMC9s) can promote food allergy mediated by IgE." (PMID 32228589, 2020). "IL-9 transgenic mice showed that IL-9-mediated mast cell responses play an important role in food allergy and oral antigen sensitisation." (PMID 30744042, 2019). "These effector cells then release a collection of Th2 cytokines (IL-4, IL-5, IL-9, IL-13, IL-15 and IL-18) that are organized in the intestinal immune system for prompting food allergy or anaphylactic immune responses upon successive exposure to the antigen." (PMID 27840774, 2015). "These effector cells, through exposure to an array of Th2 cytokines (IL-4, IL-5, IL-9, IL-13, IL-15 and IL-18) in the intestinal immune system, are primed for food allergy or anaphylactic reactions upon subsequent antigen exposure." (PMID 27840774, 2015). "IL-9 was recently shown to be involved in the development of food allergies, conditions known to also implicate mast cells." (PMID 22413008, 2012). "Apparently, IL-9 promotes mast cell mediated intestinal permeability and plays a role in the development of food allergies." (PMID 22413008, 2012). "IL-9 has been shown to increase the number of intestinal MC in food allergy." (PMID 37998337, 2023). "IL-9 gene expression is elevated in the intestine of individuals with food allergy, although this may also be derived from a unique subset of IL-9-producing mast cells termed MC9 cells." (PMID 36880703, 2023).
food allergy (continued). "In addition to IL4 and IL17, IgE-mediated intestinal pathological changes in food allergy are driven by IL-9." (PMID 36364962, 2022). "Although a well-known source of IL-9 is helper T cells, it has recently been shown that a population of MMCs, termed IL-9-producing MMCs (MMC9s), is a critical source of IL-9 in IgE-mediated food allergy." (PMID 35159139, 2022). "Individuals with food allergies typically develop Type 2 responses to the allergen, including the production of a number of pro-inflammatory cytokines that drive allergic responses, such as interleukin (IL)-4, IL-5, IL-9, and IL-13 from Th2 and ILC2 cells." (PMID 35769569, 2022). "Similarly, in food allergy, effects of IL-9 production were also reported in mastocytosis and intestinal permeability." (PMID 31936604, 2020). "Of interest, these cells can secrete prodigious amount of IL-9, a pleiotropic cytokine produced by both innate and adaptive immunity cells, suggesting that IL-9 and MCs may synergize to develop food allergy." (PMID 31867008, 2019). "Future studies of CD4+ T cells in egg-allergic individuals will determine whether the IL-9 is being produced by Th9 or Th2 cells, and highlights the potentially central role of IL-9 in food allergy as indicated by studies in mouse models." (PMID 27788149, 2016). "IL-9 induced mastocytosis and subsequent increase in intestinal permeability mediates intestinal anaphylaxis in a murine model for food allergy independent of other Th2 associated effectors." (PMID 24516385, 2014). "In addition, the importance of IL-9 in food allergies has been gradually elucidated." (PMID 34177881, 2021). "Abrocitinib, an inhibitor of JAK1 that is part of the signaling complex downstream of a number of cytokine receptors including IL-4, IL-13, IL-9, and TSLP, is also in a phase I trial for the treatment of food allergy (NCT05069831)." (PMID 36880703, 2023). "It is not clear whether ILC2-derived IL-9 and MMC9 interact with each other and affect food allergies." (PMID 34177881, 2021).